ENSG00000256029 (novel protein)
Gene: Protein-coding gene on chromosome 1 (159,834,474 to 159,873,053, reverse strand). Ensembl gene ENSG00000256029.
Genetic constraint (gnomAD): Missense variants: 84 observed, 83.33 expected, observed/expected ratio (o/e) 1.01, 90% interval 0.84 to 1.21. Synonymous variants: 29 observed, 30.43 expected, observed/expected ratio (o/e) 0.95, 90% interval 0.71 to 1.3.